PGAM5 (PGAM family member 5, mitochondrial serine/threonine protein phosphatase)
Diseases named in the same sentence as PGAM5 in open-access papers (continued):
Sharing a sentence is not in itself a finding about the gene and the disease.
cardiac hypertrophy (1 paper, 2024). "The efficacy and safety of PGAM5 inhibitors in the treatment of cardiac hypertrophy was validated in this study, highlighting the need for further investigation." (PMID 39309432, 2024). "We demonstrated that Otud1 promoted cardiac hypertrophy by stabilizing Pgam5 protein expression, leading to elevated Ask1 phosphorylation." (PMID 39309432, 2024). "In terms of pathogenesis, Otud1 plays a crucial role in cardiac hypertrophy by targeting Pgam5, leading to the robust activation of the Ask1-p38/JNK signal pathway to accelerate cardiac hypertrophy." (PMID 39309432, 2024). "To test the role of PGAM5 in pathological cardiac hypertrophy, we used PGAM5 inhibitor LFHP-1c (HY-139598, MCE) in TAC mice." (PMID 39309432, 2024). "Mechanistically, OTUD1 facilitated the procession of cardiac hypertrophy by directly binding to and deubiquitinating PGAM5 in a manner dependent on K63 ubiquitin chains, leading to enhanced ASK1 phosphorylation and p38/JNK MAPK signal pathway activation in cardiomyocytes." (PMID 39309432, 2024).
colon cancer (1 paper, 2023). "Yet in colon cancer, PGAM5’s pro-tumor survival effect is correlated to lipid metabolism." (PMID 37835490, 2023). "In colon cancer, PGAM5 has been linked to tumor lipid metabolism, which has not been explored in HCC." (PMID 37835490, 2023).
colorectal cancer (1 paper, 2016). A primary or metastatic malignant neoplasm that affects the colon or rectum. "The model for PGAM5 as a convergence point in promoting necroptosis arose from experiments using the human colorectal cancer cell line, HT-29 cells." (PMID 26807733, 2016).
cutaneous melanoma (1 paper, 2022). A primary melanoma arising from atypical melanocytes in the skin. "This implies that overexpression of PGAM5, a necroptosis-associated gene, promotes cutaneous melanoma progression." (PMID 36523972, 2022). "In this study, a bioinformatics approach was used to identify PGAM5, a biomarker whose high expression is associated with the poor prognosis of cutaneous melanoma." (PMID 36523972, 2022). "The results showed that PGAM5 was differentially expressed in cutaneous melanoma tissues and paraneoplastic tissues and was highly expressed in tumor tissues." (PMID 36523972, 2022). "The results showed that PGAM5 was highly expressed in cutaneous melanoma and that it led to a poor prognosis." (PMID 36523972, 2022). "PGAM5 expression in cutaneous melanoma was assessed by qRT-PCR, and the results showed that PGAM5 was overexpressed in cutaneous melanoma tissues compared with its expression in normal tissues." (PMID 36523972, 2022). "The results of this study showed that PGAM5 was overexpressed in cutaneous melanoma and that it played an active role in tumor progression." (PMID 36523972, 2022). "To understand the expression and prognostic relationship between PGAM5 and cutaneous melanoma, we conducted an analysis using the TGCA database and GTEX database." (PMID 36523972, 2022). "Based on the expression level of the necroptosis-related gene set and the prognostic significance between this gene set and cutaneous melanoma, PGAM5 was selected as a key gene in this study." (PMID 36523972, 2022). "The results showed that PGAM5 was highly expressed in cutaneous melanoma tissues." (PMID 36523972, 2022). "In this study, we found for the first time that PGAM5 was overexpressed in cutaneous melanoma tissues compared with its expression levels in non-tumor tissues (P<0.001) and that PGAM5 leads to a poor prognosis." (PMID 36523972, 2022). "No direct evidence has ever established a link between PGAM5 and cutaneous melanoma." (PMID 36523972, 2022).
depression (1 paper, 2023). "Using fMRI, we found that the PFC volume of PGAM5−/− mice and PFC reward system connectivity decreased, further confirming the role of PGAM5 in depression." (PMID 37622283, 2023). "To investigate the relationship between PGAM5 and depression, we first used CUMS‐treated mice, which displayed reduced central walking distance in the OFT (p < 0.05 for Control vs. CUMS) and increased immobility time in the forced swim test (FST) (p < 0.01 for Control vs. CUMS)." (PMID 37622283, 2023).
dilated cardiomyopathy (1 paper, 2025). Cardiomyopathy which is characterized by dilation and contractile dysfunction of the left and right ventricles. "Necroptosis, neutrophil extracellular trap formation, cardiac muscle contraction, and dilated cardiomyopathy, among others, are some pathways affected by downregulated proteins such as Pgam5, Slc25a4, and H2ax as well as Myl2, Myl3, Atp2a1, and Tpm2." (PMID 41011134, 2025).
emphysema (1 paper, 2018). "However, PGAM5 expression in carcinomas from smokers with moderate emphysema showed lower expression compared to those from smokers with mild or no emphysema." (PMID 30526542, 2018). "PGAM5 expression in the alveolar macrophages was also higher in background lung from the 13 smokers with emphysema (H score, 95 ± 3.7, mean and SEM) compared to all patients without emphysema (smokers and non-smokers; 65 ± 13, p < 0.05)." (PMID 30526542, 2018).
endotoxemia (1 paper, 2023). "Our findings thus identified the Pgam5/PHB2 interaction as a promising target for the treatment of endotoxemia-related cardiac dysfunction." (PMID 37781037, 2023). "In conclusion, our findings revealed that Pgam5-mediated dephosphorylation of PHB2 critically contributes to endotoxemia-related cardiac dysfunction by preventing PHB2 mitochondrial import, which is required for activation of both mitophagy and UPRmt." (PMID 37781037, 2023). "Based on in vitro and in silico analyses, we concluded that under endotoxemia conditions, Pgam5 directly interacts with PHB2 and induces PHB2 dephosphorylation at Ser39." (PMID 37781037, 2023). "Importantly, our results showed that Pgam5-mediated dephosphorylation of PHB2-Ser39 is a novel pathological alteration that contributes to endotoxemia-mediated mitochondrial damage and cardiomyocyte death by preventing PHB2 mitochondrial recruitment." (PMID 37781037, 2023). "Herein, we report on the complex relationship between the mitochondrial serine/threonine-protein phosphatase Pgam5 and PHB2, a component of the mitochondrial prohibitin complex, in endotoxemia-mediated myocardial dysfunction." (PMID 37781037, 2023). "Given the central contribution of Pgam5 to numerous inflammation-related diseases, the design of novel drugs targeting Pgam5 seems to be a critical method for the management of endotoxemia-induced organ dysfunction." (PMID 37781037, 2023).
female infertility (1 paper, 2022). Diminished or absent ability of a female to achieve conception. "Therefore, we attempted to uncover whether the high phosphoglycerate mutant enzyme family member 5 (PGAM5) expression is associated with female infertility in cumulus cells, and aims to find out the underlying mechanism of action of PGAM5." (PMID 34995407, 2022).
glioma (1 paper, 2022). A benign or malignant brain and spinal cord tumor that arises from glial cells (astrocytes, oligodendrocytes, ependymal cells). "For the glioma TCGA cohort, the risk score was calculated as follows: risk score = (0.6457 × PGAM5 expression) + (0.8062 × SQSTM1 expression) + (−0.4834 × ATG9A expression) + (−0.6285 × GABARAPL1 expression)." (PMID 36292980, 2022).
Glucose intolerance (1 paper, 2023). Glucose intolerance (GI) can be defined as dysglycemia that comprises both prediabetes and diabetes. "A previous study already demonstrated that PGAM5-KO may alleviate obesity-related metabolic disorders (e.g. glucose intolerance)." (PMID 37605246, 2023).
hematoma (1 paper, 2026). A hematoma is a collection of blood from a vascular structure into an extravascular space. "Subsequently, immunofluorescence staining demonstrated that astrocyte‐specific knockout of Pgam5 significantly inhibited neurotoxic astrocyte reactivity in the peri‐hematoma region of ICH mice." (PMID 41201111, 2026).
Hepatic fibrosis (1 paper, 2024). The presence of excessive fibrous connective tissue in the liver. "Additionally, mild hepatic fibrosis observed in Pgam5f/f mice post-EtOH treatment was absent in Pgam5hKO mice, further underscoring Pgam5's protective role against alcohol-induced structural and functional liver abnormalities." (PMID 38464835, 2024).
Hepatitis (1 paper, 2025). Inflammation of the liver. "Here we review the structure and sublocalization of PGAM5, introduce its importance in programmed cell death and summarize its crucial roles in the development and progression of inflammatory diseases such as pneumonia, hepatitis, neuroinflammation and aging." (PMID 39930129, 2025).
Hypertension (1 paper, 2022). The presence of chronic increased pressure in the systemic arterial system. "Plasma PGAM5 is an independent biomarker for PD, especially among elderly patients (age > 60 years) and patients without hypertension." (PMID 36389083, 2022).
Infertility (1 paper, 2022). "The high expression of PGAM5 in the cumulus cells is negatively correlated with the pregnancy rate of infertile patients." (PMID 34995407, 2022). "However, the proportion of PGAM5 in older women is very high, which is also reflected through the production of ATP in the cells of infertile patients, and PGAM5 is correlated with clinical parameters of infertile patients." (PMID 34995407, 2022). "Furthermore, it was established that PGAM5 as well as DRP1 show a significant increase in the cumulus cells of the older patients experiencing infertility." (PMID 34995407, 2022). "In addition to the interaction between PGAM5 and DRP1 in this study, PGAM5 is negatively correlated with the fertilization rate and the number of fertilized eggs in CC in patients experiencing infertility." (PMID 34995407, 2022).
Insulin resistance (1 paper, 2023). Increased resistance towards insulin, that is, diminished effectiveness of insulin in reducing blood glucose levels. "With PGAM5 knockdown, insulin resistance was increased in HepG2 cells, pro-inflammatory cytokines secretion was enhanced in THP-1 and BMDM cells, and pro-fibrotic genes were up-regulated in LX2 cells." (PMID 37605246, 2023).
leukemia (1 paper, 2023). A malignant (clonal) hematologic disorder, involving hematopoietic stem cells and characterized by the presence of primitive or atypical myeloid or lymphoid cells in the bone marrow and the blood. "In human differentiated THP-1 cells (a human leukemia monocytic cell line), knockdown of PGAM5 stimulated TNFα and IL-6 secretion in naïve macropahges and increased TNFα, IL-6 and IL-1β in macropahges treated with IL-4 and IL-13 (M2 macrophage)." (PMID 37605246, 2023).
lung adenocarcinoma (1 paper, 2023). A carcinoma that arises from the lung and is characterized by the presence of malignant glandular epithelial cells. "There was a downregulation of most of necroptosis-related genes in lung adenocarcinoma (LUAD) versus lung tissues but an increase in PGAM5, HMGB1, TRAF2, EZH2 levels." (PMID 37965055, 2023).
lung squamous cell carcinoma (1 paper, 2018). "The association of PGAM5 expression with worse prognosis in squamous cell carcinoma and its expression in the sequential transformation of squamous dysplasia into malignant squamous cells suggests a pathological role for PGAM5 in lung squamous cell carcinoma." (PMID 30526542, 2018).
mesothelioma (1 paper, 2022). A usually malignant and aggressive neoplasm of the mesothelium which is often associated with exposure to asbestos. "The risk score for the mesothelioma TCGA cohort was calculated as follows: risk score = (0.782 × PGAM5 expression) + (1.545 × ATG9A expression)." (PMID 36292980, 2022).
metabolic syndrome (1 paper, 2022). A cluster of metabolic risk factors for CARDIOVASCULAR DISEASES and TYPE 2 DIABETES MELLITUS. "PGAM5 has been reported to influence progression of metabolic syndrome in multiple ways." (PMID 39285950, 2022).
Obesity (1 paper, 2023). Accumulation of substantial excess body fat. "Our data suggested that the role of PGAM5 on NASH was only prominent with the presence of obesity since PGAM5 deletion only alleviated NASH in the HFHF model with excessive energy intake and systemic fat accumulation." (PMID 37605246, 2023). "Also, our study highlighted the possibility of PGAM5 inhibitors as a novel therapeutic target for obesity and NASH." (PMID 37605246, 2023). "Our study supports PGAM5 as a novel therapeutic target for obesity and NASH." (PMID 37605246, 2023). "Recent studies reported that knockout of PGAM5 showed resistance against cold and fasting-induced metabolic stress and high-fat-diet (HFD) -induced obesity, indicating PGAM5 may act as a metabolic regulator." (PMID 37605246, 2023).
osteoarthritis (1 paper, 2024). A noninflammatory degenerative joint disease occurring chiefly in older persons, characterized by degeneration of the articular cartilage, hypertrophy of bone at the margins and changes in the synovial membrane. "Conditional knockout of both PGAM5 and β-catenin in macrophages significantly exacerbated osteoarthritis compared to PGAM5-deficient mice." (PMID 38433252, 2024). "To address the role of macrophage PGAM5 in osteoarthritis, we generated Pgam5fl/fl -lyz2-Cre (Pgam5 cKO) mice, by crossing Pgam5fl/fl mice with transgenic mice that carried lysozyme (Lyz2) proximal promoter - mediated Cre recombinase, which specifically ablates PGAM5 from macrophages." (PMID 38433252, 2024).
psoriasis (1 paper, 2021). An autoimmune condition characterized by red, well-delineated plaques with silvery scales that are usually on the extensor surfaces and scalp. "As PGAM5 activates mainly caspase 9, it may be responsible for its activation in psoriasis." (PMID 34576119, 2021).
REM sleep behavior disorder (1 paper, 2022). A disorder characterized by episodes of vigorous and often violent motor activity during rem sleep (sleep, rem). "Notably, plasma PGAM5 levels combined with plasma oligomeric α-synuclein (α-syn) and the score of the REM sleep behavior disorder questionnaire-Hong Kong (RBDQ-HK) showed AUC values of 0.80 and 0.82." (PMID 36389083, 2022).
schizophrenia (1 paper, 2024). A major psychotic disorder characterized by abnormalities in the perception or expression of reality. "Finally, we identified CSNK2B, TOMM40, MAP1LC3B, MFN1, CSNK2A2, PGAM5 and ATG12 as the diagnostic genes for schizophrenia." (PMID 39355378, 2024).
tuberculosis (1 paper, 2017). A chronic, recurrent infection caused by the bacterium Mycobacterium tuberculosis. "In the M. marinum/zebrafish model of tuberculosis, TNFα excess leads to RIPK1-RIPK3 dependent cell death, involving PGAM5 and mitochondrial ROS production." (PMID 28892415, 2017). "In the M. marinum/zebrafish model of tuberculosis, TNFα excess leads to RIPK1-RIPK3 dependent cell death mediated through phosphoglycerate mutase family member 5 (PGAM5) and mitochondrial reactive oxygen species (ROS) production." (PMID 28892415, 2017).
tumor (33 papers, 2015 to 2026). "Taken together, these findings establish a previously unappreciated role of SND1 and the association of mitochondrion-localized SND1 with PGAM5 in mitophagy and tumor progression." (PMID 35433434, 2022). "Moreover, PGAM5 expression was negatively associated with PJA1 expression in tumours in our mouse xenograft model." (PMID 38906860, 2024). "Overexpression of PGAM5 has been shown to impart a pro-tumor effect through enhanced mitophagy and inhibition of apoptosis." (PMID 40361499, 2025). "Targeting PGAM5 in tumor cells reduces mitochondrial DNA stress and suppresses M2 polarization via the TLR9/NF-κB/CCL2 axis, significantly improving the efficacy of immunotherapy in liver cancer." (PMID 41459510, 2025). "In HCC, PGAM5 depletion reduced tumor growth through a decrease in mitophagy, enhanced apoptosis, and increased ATP production." (PMID 39063217, 2024). "Compared with the control group, the PJA1-knockdown group exhibited reduced tumour growth in terms of size, volume and weight, and the reductions in these parameters were almost reversed by PGAM5 knockdown." (PMID 38906860, 2024). "In CRC, expression of PGAM5 proteins and the mitophagy-related protein parkin are elevated in tumor tissue and correlate with advanced CRC." (PMID 39063217, 2024). "More importantly, the binding ability of SND1 and PGAM5 was further enhanced upon FCCP or glucose deprivation treatment, suggesting that the binding of SND1 and PGAM5 plays an important role within the tumor microenvironment." (PMID 35433434, 2022). "For instance, depleting PGAM5 expression inhibited tumor growth and increased the 5-fluorouracil sensitivity of LIHC cells, and high PGAM5 expression was associated with an unfavorable prognosis in LIHC patients." (PMID 35855852, 2022). "Previously, necroptosis was found to promote the immunity of NKT cells by increasing RIP3 gene expression and activating PGAM5, which exerted a tumor suppressive function." (PMID 36035126, 2022). "By performing cell growth and xenograft assays, we find that SND1-induced mitophagy promotes cell proliferation and tumor progression, depending on PGAM5 and its mitochondrial localization." (PMID 35433434, 2022). "Previous studies have reported that depleting PGAM5 inhibits tumor development and enhances the 5-fluorouracil sensitivity of HCC cells." (PMID 36304466, 2022). "S100A9 and PGAM5 expression was significantly upregulated in tumor tissues compared with normal liver tissues." (PMID 36041055, 2022). "Together, these results indicated that PGAM5 enhanced tumor cell proliferation and inhibited apoptosis." (PMID 30250224, 2018). "Correlation analysis of both the testing cohort (TMUCH patients) and validation cohort (SYSUCC patients) demonstrated that PGAM5 overexpression was positively correlated with more advanced clinical stages and tumor relapses (p < 0.05)." (PMID 30250224, 2018). "Blocking the interaction between PGAM5 and Bcl-xL resulted in Bcl-xL degradation and inhibited the pro-tumor functions of PGAM5." (PMID 30250224, 2018). "According to the scoring criteria detailed above, PGAM5 was strongly up-regulated in HCC tissues compared with adjacent non-tumor tissues (**p < 0.01)." (PMID 30250224, 2018). "In conclusion, these observations suggest a new model for PGAM5 function as a protective mediator of necroptosis in vivo, which is in contrary to its roles in tumor cell lines." (PMID 26807733, 2016). "In cancer, overexpression of PGAM5 promotes antioxidant tumor defense mechanisms." (PMID 40361499, 2025). "In summary, the clinical potential of CAR-M therapy is becoming evident, while targeting key nodes in macrophage polarization—such as Furin, PAD4, and PGAM5—and their combination with existing therapies like PD-1 inhibitors are opening new avenues for enhancing anti-tumor immune responses." (PMID 41459510, 2025).